FGFR2 (fibroblast growth factor receptor 2)
Diseases named in the same sentence as FGFR2 in open-access papers (continued):
Sharing a sentence is not in itself a finding about the gene and the disease.
breast carcinoma (continued). "Fusion partners of FGFR2 reported specifically in breast cancer are AFF3, CASP7 and CCDC6, while partners identified in other cancers include TACC and KIAA family members, PPHLN1, NTRK1, BICC1, AHCYL1, OFD1 and SLC45A3." (PMID 34344433, 2021). "In the TCGA dataset, 126 out of 994 (13%) breast cancer patients have FGFR2 (7%) and/or FGFR4 (6%) alterations." (PMID 34344433, 2021). "Inhibition of FGFR2, which is widely expressed in human breast cancers, can be combined preclinically with immune checkpoint antibodies to enhance anticancer immunotherapy, warranting clinical evaluation of personalized targeted therapy." (PMID 34514747, 2021). "For 31 hormone receptor (HR)+/HER2− breast cancers, there were two clusters: One with the co-occurrence of ATM, FGFR1, and WT1 frameshift mutations, and the other with JAK3 splice site and FGFR2 frameshift mutations." (PMID 34203389, 2021). "Next, we investigated the expression of FGFR2 and PD‐L1 using IHC in a tissue array comprising 415 human breast cancer samples." (PMID 34514747, 2021). "In the METABRIC dataset, 247 out of 1904 (13%) breast cancer patients have FGFR2 (6%) and/or FGFR4 (7%) alterations." (PMID 34344433, 2021). "FGFR2 amplification, which occurred in 26 (1.4%) and 15 (1.5%) breast cancer patients in the METABRIC and TCGA datasets, respectively, was observed in all subtypes except the claudin-low subtype." (PMID 34344433, 2021). "As FGFR2 is widely expressed in human breast cancers, this discovery is a putative novel therapeutic option for human tumors expressing FGFR2 and PD‐1 or PD‐L1." (PMID 34514747, 2021). "This solution was also enriched in genes known to be associated with breast cancer susceptibility (BLM, CASP8, CASP10, DNAJC1, FGFR2, MRPS30, and SLC4A7, P-value = 3 × 10−4)." (PMID 33735170, 2021). "Interrogation of public datasets revealed FGFR2 amplification, fusion or mutation in TNBC and other breast cancer subtypes, while FGFR4 overexpression and amplification occurred in all breast cancer subtypes and were associated with poor prognosis." (PMID 34344433, 2021). "Rsk and Plk1 both suppress DNA-damage checkpoint signaling by phosphorylating and inhibiting MRE11 activity, whilst FGFR2 regulates MRE11 expression through the MEK/ERK/POU1F1 pathway in breast cancer." (PMID 33927349, 2021). "Similar to a FGFR3-TACC3 fusion in TNBC previously characterized by ourselves and others, FGFR2 fusions only occur at a very low frequency in breast cancer." (PMID 34344433, 2021). "FGF10 promotes tumor invasion and metastasis by binding to FGFR2 in pancreatic cancer and breast cancer cell lines." (PMID 33034614, 2020). "For instance, genome-wide association studies performed by the Breast Cancer Association Consortium showed that BRCA2, CHEK2, ESR1, FGFR2, MDM4 and PIK3R3 carry germline variants associated with BC development." (PMID 32210335, 2020). "The amplification of the FGFR2 locus (10q26) is a rare event in breast cancer, as it occurs in less than 1% of all cases." (PMID 33081025, 2020). "Since FGFR2 can confer tamoxifen resistance in estrogen-positive breast cancer cells, it is feasible that neferine also reverses FGFR2-mediated tamoxifen resistance." (PMID 33066509, 2020). "The aim of the study was to contest AI with human expertise in a quantitative and qualitative analysis of immunostaining for FGFR2 in a cohort of breast cancer specimens." (PMID 33297384, 2020).
breast carcinoma (continued). "Multiple FGFR2 dysregulations have also been detected in breast cancer, lung cancer (both adenocarcinoma and squamous cell carcinoma), and intrahepatic cholangiocarcinoma, in which fusions of FGFR2 constitute an oncogenic potential for this aberration." (PMID 33352931, 2020). "The amplification of FGFR1 represents the most frequent genomic alteration in breast cancer, whereas the amplification of the FGFR2-4 genes is less common." (PMID 33081025, 2020). "The detail molecular mechanism of TA2 spontaneous breast cancer is very complex and more experiments are needed to confirm the relationship between FGFR2/STAT3 signaling pathway and the tumorigenesis in TA2 mice in the future." (PMID 32432040, 2020). "In particular, SNP variants in the fibroblast growth factor receptor-2 (FGFR-2) gene and/ or the FGFR-2 promoter are associated with an increased risk of breast cancer in Chinese women, Northern Indian, Caucasian, and AA women." (PMID 32714862, 2020). "The finding of nuclear expression of FGFR2 has been observed before in other tumour entities such as breast cancer." (PMID 32522271, 2020). "Some of the listed genes already have functional data linking breast cancer CCVs and somatic point mutations to altered target gene expression, including ESR1, FGFR2, and MAP3K1." (PMID 31910858, 2020). "In this vein, the amplification of the FGFR1 and FGFR2 gene loci has been described as recurrent in this breast cancer subtype." (PMID 33081025, 2020). "It was recently shown that treatments with neferine restrain the proliferation, migration, and invasion of breast cancer cells via downregulating miR-374a, which positively controls FGFR2 levels." (PMID 33066509, 2020). "Fibroblast growth factor receptor 2 (FGFR2) is known to be overexpressed in subsets of breast cancer tissues and is negatively correlated with the overall survival of breast cancer patients." (PMID 33066509, 2020). "We present here an assessment of a ‘real-life’ value of automated machine learning algorithm (AI) for examination of immunohistochemistry for fibroblast growth factor receptor-2 (FGFR2) in breast cancer (BC)." (PMID 33297384, 2020). "We found that the mutation frequency of ERCC6 (1.8%) in breast tumors was similar to those of known breast cancer susceptibility genes, such as BRCA1 (2.9%), BRCA2 (2.9%), BLM (1.9%), FGFR2 (1.5%), and CHEK2 (1.0%)." (PMID 33277540, 2020). "Experimental studies using lapatinib-resistant HER2+ breast cancer cells have found the amplification and overexpression of the FGFR2 levels." (PMID 33081025, 2020). "While the roles of FGFR1 and FGFR2 in breast cancer have been studied in considerable detail, FGFR3 remains poorly characterized in this setting." (PMID 31987043, 2020). "Interaction between fibroblast growth factor receptor 2 (FGFR2) and estrogen/progesterone receptors (ER/PR) affects resistance to anti-ER therapies, however the prognostic value of FGFR2 in breast cancer (BCa) remains largely unexplored." (PMID 32971804, 2020). "In transplantation experiments with MFM-223 breast cancer cells (a cell line with 287 genomic copies of FGFR2), the administration of GP369 prevents tumor growth." (PMID 32676501, 2020). "The method reveals that ESR1, FGFR2, VDR, CNTNAP2, and BRCA2 have a weak association with sporadic breast cancer in the Uruguayan population." (PMID 33126731, 2020). "They found 4 SNPs associated with a higher breast cancer risk, two of which, rs3803662 in TOX3 and rs2981579-A (FGFR2), are consistent with our findings." (PMID 31125336, 2019). "Among the previously reported loci, FGFR2 on chr10q26.13 and TOX3-CASC16 on chr16q12.1 are the two most significant associated breast cancer susceptible loci across different populations, followed by MAP3K1 on chr5q11.2 and CCDC170-ESR1 on chr6q25.1." (PMID 31757997, 2019).
breast carcinoma (continued). "Clearly, the composition of significant gene sets in any breast cancer pathway analysis will depend on the number of times FGFR2 and select other genes appear in the pathway definition database." (PMID 30875371, 2019). "At several of the ER+ risk loci, including the 10q26.13-rs2981579 (FGFR2) and 14q13.3-rs2236007 (PAX9) risk loci, we observed interaction peaks that were restricted to the two ER+ breast cancer cell lines and the normal breast epithelial cell line." (PMID 29531215, 2018). "A previous analysis of the CGEM data reported only two genes, FGFR2 and BUB3, as risk factors for breast cancer." (PMID 29965997, 2018). "A missense mutation or increased copy number of the FGFR2 gene is present in breast cancer and GC to activate FGFR2 signaling." (PMID 29987267, 2018). "The FGFR4 rs1966265 and FGFR2 rs2981578 contributed to clinical outcome of breast cancer treated with docetaxel–epirubicin-cyclophosphamide (CET)-based chemotherapy." (PMID 30359238, 2018). "For example, anti-FGFR2 antibodies displayed high efficacy in mice against FGFR-overexpressing breast cancer (GP369 and GAL-FR22) and gastric cancer (GAL-FR21) xenografts." (PMID 30134556, 2018). "Of note, there were no LoF variants detected and no excess of missense variants (four in cases versus four in control participants) in FGFR2, the “top hit” in many independent breast cancer GWASs." (PMID 29316957, 2018). "The FGFRs harbour genetic aberrations such as amplifications of FGFR1, FGFR2 and FGFR4 and mutations in FGFR2 and FGFR4 genes in breast cancer." (PMID 29455658, 2018). "In breast cancer, FGFR1 amplification is the most frequent genomic aberration, whereas the FGFR2–4 gene amplifications and FGFR activating mutations are uncommon." (PMID 30011957, 2018). "The examples include: GP369, an antibody specific for FGFR2, or BAY1187982—an anti-FGFR2 antibody-drug conjugate, that both have shown successful results on gastric and breast cancer models." (PMID 30134556, 2018). "The association between fibroblast growth factor receptor 2 (FGFR2) polymorphism and breast cancer (BC) susceptibility remains inconclusive." (PMID 27966449, 2017). "Of the 94 enrolled patients initially, partial responses were seen in 4 FGFR3 mutated bladder cancers, 2 FGFR1 amplified SqCLC, and a reduction in tumor burden was seen in FGFR2 fusion cholangiocarcinoma as well as in FGFR1 amplified breast cancer." (PMID 28030802, 2017). "Fox2 (Forkhead box protein 2) is overexpressed in breast cancer cells and one of its target genes is FGFR2." (PMID 28881705, 2017). "Proof of efficacy has been seen in pre-clinical studies demonstrating successful monotherapy for inhibiting tumor growth in gastric and breast cancer xenograft models that demonstrate FGFR2 overexpression." (PMID 28030802, 2017). "FGFR2 is a member of the FGFR family of receptor tyrosine kinases that has been found to be overexpressed in some breast cancer cell lines." (PMID 26911390, 2016). "We have focused on the FGFR2 locus, which showed the strongest association with ER status, particularly among HER- breast cancer patients." (PMID 27764800, 2016). "SNP rs79619171 in the FGFR2 region is a splice site donor in the TACC2 gene; it was observed only in the Japanese American samples (MAF 0.08) and was moderately associated with breast cancer (OR 1.47, 95 % CI 1.09–1.98, p = 0.01)." (PMID 27814745, 2016). "And, in FGFR2 amplified breast cancer cell lines, constitutive signaling appeared to confer a survival advantage over non amplified cell lines." (PMID 27154171, 2016). "FGFR1 was shown to be amplified in breast cancer and lung cancer, FGFR2 in breast cancer and gastric cancer." (PMID 27409346, 2016). "FGFR2 gene amplification was reported in approximately 1–2 % of all breast cancers and in about 4 % of triple-negative tumours (TNBC)." (PMID 27476168, 2016).
breast carcinoma (continued). "Due to the common nature of the risk alleles at this locus, it is believed that the locus contributes to up to 16% of all breast cancers, suggesting a significant disease burden due to FGFR2." (PMID 27236187, 2016). "Using TaqMan SNP Genotyping Assays, we evaluated FGFR2 rs2981582, TNRC9 rs3803662, TNRC9 rs12443621, and LP1 rs3817198 polymorphisms in 487 subjects, including 105 breast cancer cases and 382 controls." (PMID 26911390, 2016). "In this study, we examine the effect of FGFR2 activation on the transcriptional profiles of ER+ breast cancer cell lines." (PMID 27236187, 2016). "FGF10 is an oncogene that binds to FGFR2 and is overexpressed in ∼10% of human breast cancers, whereas MRPS30 plays a key role in apoptosis." (PMID 27640304, 2016). "Here, we demonstrate that in breast cancer cell lines FGFR2 signalling is able to oppose the effect of oestrogen signalling." (PMID 27236187, 2016). "This supports the validity of the screen as FGFR2 was already known to be involved in breast cancer stem cell maintenance." (PMID 27829216, 2016). "In Latinas, 4 (MAP3K1, ZMIZ1, FGFR2, and TOX3) of the 12 regions have been associated with breast cancer in 1497 cases and 3213 controls." (PMID 27814745, 2016). "TICs isolated from human and mice mammary tumours were found to be enriched with FGFR2-overexpressing population." (PMID 27476168, 2016). "In a phase II clinical trial (NCT01795768), AZD4547 showed therapeutic efficacy as a second-line treatment in patients with FGFR1- and FGFR2-amplified breast cancer, squamous cell carcinoma of the lung, or gastro-esophageal adenocarcinoma." (PMID 26555375, 2015). "Recently, overexpression of FGFR-2 in breast cancer cell lines was reported to lead to constitutive FGFR-2 activation." (PMID 26465941, 2015). "For example, the fibroblast growth factor receptor 2 (FGFR2) is generally regarded as an oncoprotein in breast cancer." (PMID 25794154, 2015). "All breast cancer cells secrete high mount of FGF2 as well as express higher FGFR2 protein than FGFR1, and the level is much higher than in Hs 578Bst cells." (PMID 26575424, 2015). "As illustration, we apply our method to a study of young-onset breast cancer and find that it improved precision for SNPs in FGFR2 and that estimated relative risks based on triads are closely replicated using the parental data." (PMID 26157456, 2015). "For example, we identified both known and new endometrial cancer hotspots in the tyrosine kinase domain of the FGFR2 protein, one of which is also a hotspot in breast cancer, and found new two hotspots in the Immunoglobulin I-set domain in colon cancer." (PMID 25794154, 2015). "The NHGRI GWAS catalog (accessed on 17th September 2014) identified 21 published GWAS linking TERT to breast cancer, bladder cancer, testicular cancer, lung cancer, glioma and prostate cancer and 11 GWAS linking FGFR2 to breast cancer." (PMID 26431041, 2015). "Because FGFR2 amplification can drive gastric and breast cancer cell growth, we searched for additional cell lines that harbor similar FGFR2 copy gain." (PMID 24968263, 2014). "Concerning the possible link between FGF/FGFR and drug resistance to EGFR-TKIs, we have previously demonstrated amplification of the FGFR2 gene in lapatinib-resistant breast cancer cells." (PMID 25115383, 2014). "In some case-control studies, certain polymorphisms in fibroblast growth factor receptor 2 (FGFR2) and methionine synthase reductase (MTRR) were indicated to elevate individual susceptibility in postmenopausal breast cancer." (PMID 25531440, 2014). "We also treated cells with MK2461, a Met kinase small molecule inhibitor that also inhibits FGFR2 phosphorylation and growth of FGFR2 amplified gastric and breast cancer cell lines." (PMID 24968263, 2014). "For BRCA2 carriers, SNPs at loci 10q26 (FGFR2) and 16q12.1 (TOX3) were associated with all subtypes of breast cancer." (PMID 25919761, 2014).
breast carcinoma (continued). "Frequencies of inferred haplotypes of FGFR2 SNPs rs7895676, rs2981578, rs2981582 and rs1219648 in breast cancer cases and controls." (PMID 25333473, 2014). "For FGFR2 amplification, 5 of 7 studies were in gastric cancer, and the other 2 studies were in breast cancer and lung cancer." (PMID 25171497, 2014). "Aberrant expression of alternatively spliced isoforms of FGFR2 has been shown to activate signal transduction leading to transformation in breast cancer cells." (PMID 25333473, 2014). "For BRCA1 carriers, there were significant differences (Phet <0.01) in the HR for high grade (grade 3) and grades 1 and 2 breast cancer for SNPs at 10q26.12 (FGFR2) and at 12q24.21." (PMID 25919761, 2014). "Recent identification of these intron 2 SNPs has drawn substantial attention towards FGFR2 as a candidate gene for breast cancer." (PMID 25333473, 2014). "In this article, we showed that FGFR1 is amplified in lung cancer, breast cancer and, rarely, in pancreatic cancer and squamous cell cancer, whereas FGFR2 amplification mainly occurs in gastric cancer and breast cancer." (PMID 25171497, 2014). "Deregulation of FGF signaling is observed in breast cancer, with FGFR2 amplification and overexpression observed in 5–10% of human breast cancers, correlating with poor prognosis." (PMID 25079073, 2014). "Inclusion of FGFR2 increased the difference in detection rate between male and female breast cancer (detection rate of female breast cancer 85.0% vs. male breast cancer 72.9%, p = 0.004)." (PMID 23308200, 2013). "Amplification or overexpression of FGFR2 was observed in 5-10% of breast tumors and breast cancer cell lines." (PMID 24171766, 2013). "We selected AXIN-1, FAS, and FGFR2 for further analysis because of their known role in breast cancer and apoptosis." (PMID 23758675, 2013). "Findings from previous studies suggested that several SNPs are predominantly associated with ER+ breast cancer: TNRC9-rs3803662, 5p12-rs4415084, 5p12-rs10941679, FGFR2-rs2981582 8q24-rs13281615." (PMID 23894282, 2013). "Further, FGFR2 expression in female breast cancer was highly correlated with ERα, PR expression and low grade, and with cancers in patients with a BRCA2 mutation." (PMID 23308200, 2013). "We also showed that MEK1/2 and STAT3 stimulation in response to FGF1 stimulation is increased in HEK293 cells expressing the FGFR2-IIIb breast cancer mutants." (PMID 23527311, 2013). "Nonetheless, data presented in this study suggest FGFR2 is a target for overcoming anti-estrogen resistance in breast cancer." (PMID 23758675, 2013). "Compared to female breast cancer, IGF1-R was more frequently expressed in male breast cancer (p<0.001), while MET and FGFR2 were less frequently expressed (both p<0.001) in male breast cancer." (PMID 23308200, 2013). "However, the mechanism by which FGFR2 functions as a risk factor in breast cancer remains unknown." (PMID 23300950, 2013). "FGFR2 signaling has also been found to be important in many human cancers, such as prostate cancer, bladder cancer, gastric cancer, breast cancer and melanoma." (PMID 24386391, 2013). "Notably, inspection of the structure of the receptor showed that the breast cancer mutation is located in the intracellular tyrosine kinase domain adjacent to the activation loop suggesting that it might affect the tyrosine kinase activity of FGFR2." (PMID 23527311, 2013). "This is the first report demonstrating convergence of two recent findings: FGFR2 function in breast cancer and in normal mammary stem cell maintenance." (PMID 23300950, 2013). "FGFR2 was included in this analysis because it is one among 19 genes that undergo breast cancer-specific alternative splicing, which results in proteins with distinct functional domains." (PMID 23758675, 2013). "Compared to female breast cancer, IGF1-R expression was higher and MET and FGFR2 expression lower in male breast cancer." (PMID 23308200, 2013).